PEAK3 (PEAK family member 3)
Description:
Probable catalytically inactive kinase (Probable). Interacts with CRK-II and antagonizes CRK-II-signaling. Prevents the formation of CRK-II-dependent membrane ruffling and lamellipodia-like extensions.
Synonyms: C19orf35; FLJ45778
Tractability: No criterion of Open Targets' tractability assessment is met for any kind of drug.
Gene: Protein-coding gene on chromosome 19 (2,274,631 to 2,282,175, reverse strand). Ensembl gene ENSG00000188305.
Subcellular location (Human Protein Atlas): Cytosol
Gene Ontology:
Molecular function: protein binding; protein kinase activity
Biological process: regulation of actin cytoskeleton organization; regulation of cell shape; regulation of cell motility
Cellular component: actin cytoskeleton; focal adhesion
Genetic constraint (gnomAD): Loss-of-function variants: 18 observed, 12.16 expected, observed/expected ratio (o/e) 1.48, 90% interval 1.01 to 1.91. The synonymous counts are far from expectation, so gnomAD's model fits this gene poorly and the ratio says little. Missense variants: 739 observed, 512.36 expected, observed/expected ratio (o/e) 1.44, 90% interval 1.36 to 1.53. Synonymous variants: 347 observed, 252.17 expected, observed/expected ratio (o/e) 1.38, 90% interval 1.26 to 1.5.
Homologues: Orthologues: chimpanzee PEAK3 (99% identical), macaque PEAK3 (87% identical), dog PEAK3 (71% identical), pig PEAK3 (70% identical). Paralogues in human: PEAK1 (30% identical), PRAG1 (29% identical), PINK1 (16% identical).
Diseases named in the same sentence as PEAK3 in open-access papers:
PEAK3 is named in the same sentence as 8 diseases in open-access papers, as found by Europe PMC text mining. Sharing a sentence is not in itself a finding about the gene and the disease. The quoted sentences say what the papers report.
acute myeloid leukemia (3 papers, 2021 to 2023). Acute myeloid leukemia (AML) is a group of neoplasms arising from precursor cells committed to the myeloid cell-line differentiation. "Moreover, the PEAK3 protein is strongly expressed in human hematopoietic cells and is upregulated in acute myeloid leukemia." (PMID 34944965, 2021). "Importantly, in osteosarcoma and acute myeloid leukemia (AML) cell lines, overexpression of PEAK3 results in elevated AKT activity and increased cell growth." (PMID 37336883, 2023). "PEAK3, a member of the new kinase family 3 (NKF3) mediating cell motility and tumor progression, has been identified as a therapeutic target for acute myeloid leukemia (AML) treatment." (PMID 34571936, 2021).
sarcoma (1 paper, 2021). A usually aggressive malignant neoplasm of the soft tissue or bone. "Functionally, PEAK3 overexpression in U2OS sarcoma cells enhanced their growth and migratory properties, while its silencing in THP1 leukemic cells reduced these effects." (PMID 34944965, 2021).
tumor (5 papers, 2021 to 2023). "PEAK3 overexpression enhanced cancer cell growth and migration, while its silencing reduced these pro-tumor effects." (PMID 34944965, 2021). "We recently confirmed phosphorylation of the PEAK3 TYSNL (pY24) motif in cells and showed this is required for recruitment of Grb2, and possibly CrkII and ASAP114, an Arf GTPase-activating protein that regulates cytoskeletal remodeling and is associated with tumor progression and invasiveness." (PMID 37336884, 2023). "Our findings indicate that PEAK3 is expressed in hematopoietic cells and that its expression can be deregulated in AML, suggesting a pro-tumor function." (PMID 34944965, 2021).
cancer (4 papers, 2021 to 2023). A tumor composed of atypical neoplastic, often pleomorphic cells that invade other tissues. "Several groups including ours have linked PEAK1_3 pseudokinases to cancer (i.e., PEAK1/Sgk269, PEAK2/Pragmin/SgK223/NACK, and PEAK3/C19orf35)." (PMID 35740644, 2022). "Analysis of the PEAK3 transcript level from TCGA transcriptomic data (gepia.cancer-pku.cn accessed on 2 January 2021) confirmed that PEAK3 was upregulated in AML, particularly in the M4 and M5 subtypes." (PMID 34944965, 2021). "Together, our studies provide a detailed structural snapshot of PEAK interaction networks and further elucidate how PEAK proteins, especially PEAK3, act as dynamic scaffolds that exploit adapter proteins to control signal transduction in cell growth/motility and cancer." (PMID 37336884, 2023). "We found that PEAK3 promotes cancer cell growth and migration." (PMID 34944965, 2021). "In this study, we investigated PEAK3’s functional role in cancer." (PMID 34944965, 2021).
PEAK3 also shares sentences with these, for which no sentence is quoted: colon cancers (1 paper); COVID-19 (1); gastric cancer (1); infection (1).